ITGB6 (integrin subunit beta 6)
Description:
Integrin alpha-V:beta-6 (ITGAV:ITGB6) is a receptor for fibronectin and cytotactin. It recognizes the sequence R-G-D in its ligands. Internalization of integrin alpha-V/beta-6 via clathrin-mediated endocytosis promotes carcinoma cell invasion. ITGAV:ITGB6 acts as a receptor for fibrillin-1 (FBN1) and mediates R-G-D-dependent cell adhesion to FBN1. Integrin alpha-V:beta-6 (ITGAV:ITGB6) mediates R-G-D-dependent release of transforming growth factor beta-1 (TGF-beta-1) from regulatory Latency-associated peptide (LAP), thereby playing a key role in TGF-beta-1 activation. (Microbial infection) Integrin ITGAV:ITGB6 acts as a receptor for Coxsackievirus A9 and Coxsackievirus B1. (Microbial infection) Integrin ITGAV:ITGB6 acts as a receptor for Herpes simplex virus-1/HHV-1.
Synonyms: AI1H
Tractability: Small molecule: a structure with a bound ligand is known; a high-quality ligand is known; it belongs to a druggable protein family. Antibody: a drug acting on it is in phase 2 or 3 trials; UniProt places it where antibodies can reach, with high confidence; its Gene Ontology location is reachable by antibodies, with high confidence; UniProt predicts a signal peptide or a membrane-spanning region.
Target class: Membrane receptor
Gene: Protein-coding gene on chromosome 2 (160,099,664 to 160,271,888, reverse strand). Ensembl gene ENSG00000115221.
Subcellular location: Cell membrane; Cell junction, focal adhesion
Subcellular location (Human Protein Atlas): Acrosome; Cell Junctions; Nucleoplasm; Centrosome; Connecting piece; End piece; Mid piece; Principal piece
Pathways (Reactome):
Extracellular matrix organization: ECM proteoglycans; Elastic fibre formation; Integrin cell surface interactions; Molecules associated with elastic fibres
Signal Transduction: TGF-beta receptor signaling activates SMADs
Gene Ontology:
Molecular function: coreceptor activity; molecular function activator activity; protein binding; integrin binding
Biological process: amelogenesis; cell adhesion mediated by integrin; cell adhesion; cell migration; cell-cell adhesion; cell-matrix adhesion; integrin-mediated signaling pathway; transforming growth factor beta production
Cellular component: focal adhesion; integrin alphav-beta6 complex; plasma membrane; receptor complex; cell surface; integrin complex; external side of plasma membrane; intercalated disc
Genetic constraint (gnomAD): Loss-of-function variants: 63 observed, 64.98 expected, observed/expected ratio (o/e) 0.97, 90% interval 0.79 to 1.2. The upper end of that interval is the gene's LOEUF score, 1.2, which puts it in group 5 of 6, group 1 being the genes least tolerant of losing a copy. Missense variants: 867 observed, 860.72 expected, observed/expected ratio (o/e) 1.01, 90% interval 0.95 to 1.07. Synonymous variants: 323 observed, 315.15 expected, observed/expected ratio (o/e) 1.02, 90% interval 0.94 to 1.12.
Homologues: Orthologues: macaque ITGB6 (99% identical), dog ITGB6 (95% identical), rabbit ITGB6 (94% identical), guinea pig ITGB6 (92% identical), rat Itgb6 (91% identical), mouse Itgb6 (90% identical), pig ITGB6 (88% identical), chimpanzee ITGB6 (76% identical), tropical clawed frog itgb6 (66% identical), zebrafish itgb6 (59% identical). Paralogues in human: ITGB3 (49% identical), ITGB5 (48% identical), ITGB1 (40% identical), ITGB2 (37% identical), ITGB7 (37% identical), ITGB8 (35% identical), ITGB4 (34% identical), ITGBL1 (16% identical).
Diseases named in the same sentence as ITGB6 in open-access papers:
ITGB6 is named in the same sentence as 83 diseases in open-access papers, as found by Europe PMC text mining. Sharing a sentence is not in itself a finding about the gene and the disease. The quoted sentences say what the papers report.
breast carcinoma (19 papers, 2015 to 2025). "We have identified their association with specific breast cancer subtypes and demonstrated the potential prognostic significance of ITGB6 and GDI2 in HER2+ breast cancer." (PMID 39630893, 2024). "Pathway-based representation analysis using PARADIGM revealed the activation of pathways known to be associated with ErbB receptor function and breast cancer progression, such as ITGB6." (PMID 27351228, 2016). "ITGB6 upregulation in breast cancer was associated with poor survival and metastasis." (PMID 31612115, 2019). "S9E), we used transcriptomic tumor gene expression data from the Molecular Taxonomy of Breast Cancer International Consortium (METABRIC) patient cohort to identify an ITGB6 coexpression signature in 247 patients with HER2+ breast cancer." (PMID 39630893, 2024). "Similar with our findings, serval studies have demonstrated EPS8, DSG2, ITGB6 were aberrantly expressed in pancreatic cancer, breast cancer, pituitary tumor, and gastric cancer." (PMID 36237305, 2022). "We further analyze two independent breast cancer datasets and find that specific isoforms of IGF2BP2, NECTIN4, ITGB6, and KLHDC9 are significantly associated with AZD6244, lapatinib, erlotinib, and paclitaxel, respectively." (PMID 29066719, 2017). "We have examined human breast cancer specimens (N = 460) for the expression of integrin β6 (ITGB6) mRNA by qPCR." (PMID 27184932, 2016). "Moreover, Park & al. demonstrated in MCF10 breast cancer cells overexpressing SRSF6 that ITGA5, ITGB2 and ITGB6 were overexpressed and alternative splicing variants of ITGB2, ITGB4, SRSF6 and ATXN2 were detected." (PMID 37904233, 2023). "Notably, circITGB6 has minimal effect on the expression of ITGB6, which activates the latent TGFβ and endow breast cancer immunotherapy resistance." (PMID 37898647, 2023). "MMP15 may increase the level of integrin 6 (ITGB6) by mediating Rho-Rac pathway, leading to breast cancer cell metastasis, which is consistent with the poor prognosis of breast cancer patients caused by high-level expression of MMP15 in this study." (PMID 35069702, 2021). "Potential oncogenes amplified in the breast cancer include GREB1, NRXN1, MGAT5, PKP4, DAPL1, ITGB6, and RBMS1, which may be implicated in carcinogenesis, proliferation, and invasion." (PMID 26432421, 2015). "Therefore, we examined whether ITGB6 expression might influence therapeutic efficacy of trastuzumab in HER2+ breast cancer." (PMID 39630893, 2024). "Consistent with the mechanistic data linking these molecules functionally, these analyses demonstrate that ITGB6, GDI2, and RAB5A expression positively correlate in patients with HER2+ breast cancer." (PMID 39630893, 2024). "ITGB6 can also be used as a tumor-specific surface antigen (TSA) to identify cell surface targets of CAR-T cell therapy and antibody-drug conjugates in breast cancer." (PMID 34976806, 2021). "Several top up-regulated genes were associated with motility, adhesion, invasiveness, and metastasis in breast cancer or other cancers, such as GBP1, ITGB6, ITGA2, and matrix metalloproteases MMP10 and MMP1." (PMID 27351228, 2016). "This set comprised senescence markers (CDKN1A, LMNB1, MKI67), apoptosis regulators (BCL2, BCL2L1), a highly overexpressed gene (ITGB6), and drug targets (ACTA2, GSDMC, KRT6A, PDE1A, PSMA8), all of which showed strong concordance with our RNA-seq data in all four breast cancer cell lines." (PMID 40312750, 2025). "Some genes associated with cell adhesion were analyzed from this radiation- and estrogen-induced experimental breast cancer model, including E-cadherin gene CDH1, DSC3, GJA1, the Integrin alpha 6 gene ITGA6, the Integrin beta 6 gene ITGB6, the Keratin genes KRT14, KRT16, KRT17, KRT6B, and LAMB3." (PMID 36293530, 2022). "These genes (COL9A1, ITGB8, ITGB6, TTYH1, RET, etc.)enriched in the cell adhesion may serve as important indicators of different types of breast cancer." (PMID 26273658, 2015).
breast carcinoma (continued). "Inhibition of colony formation in ITGB6-ko iCCA cells in the present study might also be induced by reduced expression of PODXL2, because PODXL2 might be necessary for the maintenance of clonogenic potential in CCA cells as indicated in breast cancer cells." (PMID 34208313, 2021).
ovarian carcinoma (16 papers, 2020 to 2025). A malignant neoplasm originating from the surface ovarian epithelium. "This was indicative of the importance of the positive feedback loop between SMYD3/ITGB6/TGFβ1 in enhancing the invasion and adhesion of ovarian cancer spheroids as well as cell–cell communication in these models." (PMID 38254117, 2024). "For example, Circ-ITGB6 accelerates ovarian cancer cisplatin resistance by inhibiting macrophage M2 polarization." (PMID 38430256, 2024). "SMYD3 also facilitated implant metastasis of ovarian cancer cells via increasing the expression of ITGB6 and ITGAM." (PMID 37386026, 2023). "In particular, we found PI3K-Akt initiators; such as the RTKs EGFR1 and VEGFA, and the integrins ITGB3 and ITGB6, to be potential drug targets in ovarian cancer patients with high CTCFL expression." (PMID 35132075, 2022). "Our study also emphasized the significance of choosing SMYD3 and ITGB6 as potential targets for the treatment of ovarian cancer transcoelomic metastasis." (PMID 34621667, 2021). "Compared with 2D-cultured HEY and A2780 cells, the corresponding 3D-cultured cells showed higher expression of SMYD3 and ITGB6, which indicated that the ovarian cancer spheroids had a more invasive phenotype." (PMID 34621667, 2021). "In conclusion, we detailed one essential pathway that contributed to the SMYD3- and ITGB6-mediated enhancement of invasion and adherence in ovarian cancer spheroids." (PMID 34621667, 2021). "ITGAM and ITGB6 have been confirmed to play critical roles in ovarian cancer invasion and implant metastasis." (PMID 33104706, 2020). "In addition, previous studies have indicated that ITGB6 promotes lipid metabolism in ovarian cancer through its interaction with the PI3K signaling pathway." (PMID 40678495, 2025). "3D spherical models of ovarian cancer have been used to shed light on the impact of both integrin beta-6 (ITGB6) and SET and MYN-domain containing 3 (SMYD3) on the activation of the TGFβ1/Smad3 pathway and downstream upregulation of N-cadherin and downregulation of E-cadherin." (PMID 38254117, 2024). "STC1 could promote metastasis, lipid metabolism and cisplatin chemoresistance via directly binding to ITGB6 in ovarian cancer." (PMID 36816947, 2023). "In our study, we found that downregulated expression of ITGB6 could reduce the activation level of the Smad3 pathway when ovarian cancer spheroids were treated with rhTGFβ1." (PMID 34621667, 2021). "To determine why SMYD3 and ITGB6 could make ovarian cancer spheroids more invasive, we downregulated the expression of SMYD3 and ITGB6 in 3D-cultured HEY and A2780 cells." (PMID 34621667, 2021). "In this report, we found that SMYD3 and ITGB6 could promote the release and activation of latent TGFβ1 and increase the phosphorylation of Smad3 activated by TGFβ1 in ovarian cancer spheroids." (PMID 34621667, 2021). "When ovarian cancer spheroids were treated with latent TGFβ1, the activation of the Smad3 pathway could also be inhibited if ITGB6 was blocked by a specific antibody." (PMID 34621667, 2021). "SMYD3 and ITGB6 activated the TGFβ1/Smad3 pathway and then induced the upregulation of Snail, Vimentin and N-cadherin and the downregulation of E-cadherin in 3D-cultured ovarian cancer spheroids." (PMID 34621667, 2021). "It is necessary to investigate whether ITGAV could regulate the activation of latent TGFβ1 in 3D-cultured ovarian cancer spheroids and whether ITGAV is involved in the ITGB6-regulated activation of latent TGFβ1 in 3D-cultured ovarian cancer spheroids." (PMID 34621667, 2021). "Although NCALD and LAMA3 are genes that show both methylation and expression changes, the methylation of the ITGB6 gene may also play a role in the chemoresistance of ovarian cancer." (PMID 34289901, 2021). "Thus, our study unmasked the mechanism of SMYD3- and ITGB6-induced ovarian cancer metastasis and provides new ideas for targeted ovarian cancer treatment." (PMID 34621667, 2021).
ovarian carcinoma (continued). "This shows that NCALD, LAMA3 and ITGB6 may influence each other and participate in the chemotherapy resistance of ovarian cancer together." (PMID 34289901, 2021). "According to reports and our research base, we speculated that SMYD3/ITGB6 promotes the invasion and adhesion of ovarian cancer spheroids by changing the configuration of TGFβ1-LAP and then activating TGFβ1." (PMID 34621667, 2021). "Previously, we found that ITGB6 could promote the invasion and adhesion of ovarian cancer spheroids." (PMID 34621667, 2021). "Our results demonstrated that the SMYD3/ITGB6/TGFβ1-Smad3 positive feedback loop could promote the invasion and adhesion of ovarian cancer spheroids by upregulating the expression of N-cadherin, Snail, and Vimentin and downregulating the expression of E-cadherin." (PMID 34621667, 2021). "In addition, TGFβ1 could also upregulate the expression of SMYD3 and ITGB6 in return to form a positive feedback loop with the SMYD3/ITGB6/TGFβ1 pathway to enhance the metastasis of ovarian cancer spheroids." (PMID 34621667, 2021). "As downstream targets of the TGFβ1/SMAD3 pathway and essential participants in EMT promotion, N-cadherin, Vimentin, E-cadherin and Snail were found to be regulated by SMYD3 and ITGB6 and could contribute to enhanced invasion and adhesion in ovarian cancer spheroids." (PMID 34621667, 2021). "However, ITGAV might be play a role in the ITGB6-regulated activation of latent TGFβ1 in 3D-cultured ovarian cancer spheroids." (PMID 34621667, 2021). "Hence, SMYD3 and ITGB6 could not only activate latent TGFβ1 but also increase the release of latent TGFβ1 from 3D-cultured ovarian cancer spheroids." (PMID 34621667, 2021). "Therefore, SMYD3 and ITGB6 could stimulate the TGFβ1/Smad3 pathway and regulate the expression of N-cadherin, Snail, Vimentin, E-cadherin in ovarian cancer spheroids and promote the EMT process." (PMID 34621667, 2021). "Using a 3D culture model to mimic the suspended growth conditions in ascites, we found that SMYD3 could enhance the adhesion and invasion of ovarian cancer spheroids and promote metastasis of ovarian cancer in vivo by upregulating the expression of ITGB6 and ITGAM." (PMID 34621667, 2021). "Moreover, SMYD3 and ITGB6 could facilitate the release of latent TGFβ1 from 3D-cultured ovarian cancer spheroids." (PMID 34621667, 2021). "In ovarian cancer, stanniocalcin 1 enhances metastatic capacity, lipid metabolism, and cisplatin resistance through the FOXC2/ITGB6 signaling pathway." (PMID 40746552, 2025). "For example, STC1 promotes ovarian cancer metastasis, lipid metabolism, and DDP chemotherapy resistance through the FOXC2/ITGB6 signalling pathway." (PMID 38556542, 2024). "In ovarian cancer, shRNA-mediated knockdown of SMYD3 decreases spheroid invasion and adhesion by suppressing integrin subunit beta 6 (ITGB6) and integrin subunit alpha M (ITGAM)." (PMID 39482529, 2024). "In these 3D models, Wnt11 was shown to negatively regulate ITGB2, ITGB6 and EpCAM while impeding the attachment of the multicellular spheroids to an ECM substrate, suggesting a role of this molecule in ovarian cancer progression." (PMID 38254117, 2024). "Inhibition of ITGB6 and ITGAM directly also resulted in decreased ovarian cancer spheroid adhesion and invasion, and this was restored with re-expression of SMYD3, ITGB6, and ITGAM." (PMID 33637115, 2021). "ChIP assays showed increased SMYD3 and H3K4me3 promoter binding at the ITGB6 and ITGAM gene loci in ovarian cancer spheroids and decreased binding with SMYD3 knockdown." (PMID 33637115, 2021). "In ovarian cancer spheroids, SMYD3 was found bind to H3K4me3 at the ITGB6 and ITGAM promoter regions to upregulate the expression of ITGB6 and ITGAM, which was verified to enhance the invasion and adhesion of ovarian cancer spheroids." (PMID 34621667, 2021).
ovarian carcinoma (continued). "Interestingly, attenuating the expression of SMYD3 and ITGB6 also decreased the release of latent TGFβ1 from ovarian cancer spheroids, which further demonstrated the regulatory roles of SMYD3 and ITGB6 in TGFβ1 pathway activation." (PMID 34621667, 2021). "Thus, the SMYD3/ITGB6/TGFβ1 positive feedback loop drove the upregulation of Snail and N-cadherin, which promoted invasion, adhesion and EMT progression during ovarian cancer metastasis." (PMID 34621667, 2021). "Hence, we determined that ITGB6-mediated TGFβ activation is involved in regulating the expression of N-cadherin, Snail, Vimentin and E-cadherin and promoting EMT progression in ovarian cancer spheroids." (PMID 34621667, 2021). "We found that anti-ITGB6 antibody was more effective in inhibiting the phosphorylation level of Smad3 in 3D-cultured NC-ITGAV cells than in 3D-cultured si-ITGAV cells, implying that ITGAV might play a role in ITGB6-regulated activation of latent TGFβ1 in 3D-cultured ovarian cancer spheroids." (PMID 34621667, 2021). "In addition, as the binding partner of ITGB6, ITGAV, had no independent effect on activating latent TGFβ1 in 3D-cultured ovarian cancer spheroids." (PMID 34621667, 2021).
pancreatic cancer (12 papers, 2019 to 2025). "As a member of the integrin β (ITGB) superfamily, the overexpression of ITGB6 is associated with the upregulation of the Notch signaling pathway in pancreatic cancer and is associated with immunosuppression in pancreatic cancer." (PMID 34976806, 2021). "Our immunohistochemical results showed that LY6D, BCAT1, and ITGB6 were all overexpressed in pancreatic cancer, which was consistent with the previous results." (PMID 34976806, 2021). "The expressions of LY6D, BCAT1, and ITGB6 in 120 cases of pancreatic cancer and 30 cases of para-carcinoma were detected by immunohistochemistry." (PMID 34976806, 2021). "A 3-gene signature consisting of LY6D, BCAT1, and ITGB6 based on 538 DEGs between both subtypes serves as a stable prognostic marker in patients with pancreatic cancer across multiple cohorts." (PMID 34976806, 2021). "Nine genetic markers, including ITGB6, can be used to predict the overall survival of patients with pancreatic cancer." (PMID 34976806, 2021). "Studies have shown that ITGB6 was a liver-metastasis-related gene for PAAD patients and the overexpression of ITGB6 was significantly associated with advanced AJCC stage and histologic grade, and worse prognosis in pancreatic cancer." (PMID 34976806, 2021). "Finally, the molecular mechanisms by which LY6D, BCAT1, and ITGB6 drive the malignant progression of pancreatic cancer require further verification." (PMID 34976806, 2021). "The LY6D, BCAT1, and ITGB6 genes were upregulated in pancreatic cancer samples." (PMID 34976806, 2021). "For instance, ITGB6 drives malignant behaviors in PC, with in vitro and in vivo studies demonstrating that ITGB6 knockdown suppresses proliferation, invasion, and migration of pancreatic cancer cells by disrupting TGF-β signaling and epithelial-mesenchymal transition (EMT)." (PMID 40486509, 2025). "Higher mRNA levels of ITGB6 and ITGB4 were detected in pancreatic cancer patients with higher histologic grades." (PMID 37779898, 2023). "In addition to protein levels, NSD3 induces global H3K36 dimethylation in pancreatic cancer cells and influences the mRNA levels for genes including ADAM28, ADAM9, BIRC3, CXCL5, DUOX2, GABRP, ITGB6, and RAB11FIP1." (PMID 37062069, 2023). "The other proteins in these pathways were members of the families of interleukin (ITGA2, ITGB6), laminin (LAMC2), and collagen (COL1A1/2, COL6A3), together with cartilage oligomeric matrix protein (COMP), whose role in pancreatic cancer has not yet been clarified." (PMID 33194391, 2020). "The roles of ITGB6 and ARNTL2 in pancreatic cancer have not been reported." (PMID 31612115, 2019).